THSD7B (thrombospondin type 1 domain containing 7B)
Synonyms: KIAA1679
Tractability: Antibody: UniProt predicts a signal peptide or a membrane-spanning region; its Gene Ontology location is reachable by antibodies, with medium confidence.
Safety:
Unwanted effects reported when the protein is acted on. In parentheses: how it was acted on, where the effect was seen, and who reports it.
alcoholism (source: ClinPGx)
Gene: Protein-coding gene on chromosome 2 (136,765,545 to 137,677,718, forward strand). Ensembl gene ENSG00000144229.
Subcellular location: Membrane
Subcellular location (Human Protein Atlas): Nucleoplasm; Cytosol
Pathways (Reactome):
Disease: Defective B3GALTL causes PpS
Metabolism of proteins: O-glycosylation of TSR domain-containing proteins
Gene Ontology:
Molecular function: protein binding
Biological process: actin cytoskeleton organization
Cellular component: plasma membrane; membrane
Genetic constraint (gnomAD): Loss-of-function variants: 132 observed, 199.88 expected, observed/expected ratio (o/e) 0.66, 90% interval 0.57 to 0.76. The upper end of that interval is the gene's LOEUF score, 0.76, which puts it in group 3 of 6, group 1 being the genes least tolerant of losing a copy. Missense variants: 1,847 observed, 1,963.3 expected, observed/expected ratio (o/e) 0.94, 90% interval 0.9 to 0.98. Synonymous variants: 718 observed, 675.61 expected, observed/expected ratio (o/e) 1.06, 90% interval 1 to 1.13.
Homologues: Orthologues: chimpanzee THSD7B (99% identical), macaque THSD7B (96% identical), rabbit THSD7B (89% identical), guinea pig THSD7B (88% identical), dog THSD7B (87% identical), pig THSD7B (87% identical), mouse Thsd7b (86% identical), rat Thsd7b (86% identical), tropical clawed frog thsd7b (61% identical), zebrafish thsd7ba (56% identical). Paralogues in human: THSD7A (50% identical), SPON1 (12% identical), SPON2 (4% identical).
Diseases named in the same sentence as THSD7B in open-access papers:
THSD7B is named in the same sentence as 24 diseases in open-access papers, as found by Europe PMC text mining. Sharing a sentence is not in itself a finding about the gene and the disease. The quoted sentences say what the papers report.
gastric cancer (4 papers, 2020 to 2026). A primary or metastatic malignant neoplasm involving the stomach. "In vitro assays, including cell proliferation, colony formation, wound healing, and Transwell invasion, were conducted following THSD7B knockdown or overexpression in gastric cancer cell lines." (PMID 42284337, 2026). "The Human Atlas database further assessed the protein expression of THSD7B across various cancers, showing upregulation in Thyroid cancer, Stomach cancer, Prostate cancer, Liver cancer, Pancreatic cancer, Lung cancer, and Colorectal cancer without significant downregulation in any cancer type." (PMID 39161765, 2024). "Few studies have focused on the biological functions of PRICKLE2, PDE12, RBP1, THSD7B, and TUBB6 in gastric cancer." (PMID 36226177, 2022).
lung adenocarcinoma (2 papers, 2020 to 2024). A carcinoma that arises from the lung and is characterized by the presence of malignant glandular epithelial cells. "Moreover, considering the frequent alterations of THSD7B, SYNE2, GRM3, and FLNC in lung squamous cell carcinoma and lung adenocarcinoma, we investigated the applicability of ITS to NSCLC patients treated with ICIs." (PMID 32969604, 2020). "Conversely, in Lung Adenocarcinoma (GBM), THSD7B exhibits a negative correlation with natural killer (NK) cells, although this association generally lacks statistical significance." (PMID 39161765, 2024).
melanoma (2 papers, 2018 to 2020). A malignant, usually aggressive tumor composed of atypical, neoplastic melanocytes. "Among the two genome-wide significant SNPs identified in the GCC-based GWAS in the Danish sample, rs71419535 is near THSD7B, which is associated with melanoma, metabolism, and Cutaneous Malignant 1 diseases." (PMID 33232274, 2020).
Pancreatic cancer (2 papers, 2022 to 2024). "A large number of studies on pancreatic cancer in Japan showed that the Thsd7b gene is significantly associated with the risk of pancreatic cancer." (PMID 35309141, 2022).
prostate carcinoma (2 papers, 2020 to 2024). A carcinoma that arises from epithelial cells of the prostate gland. "The microRNA, MIR-128-1, and two genes—CXCR4 and THSD7B—in the LCT locus all have putative roles in prostate cancer." (PMID 33193640, 2020).
breast carcinoma (1 paper, 2024). "THSD7B expression was also negatively associated with processes of breast cancer cell proliferation, migration, and invasion." (PMID 39161765, 2024). "This research has pinpointed THSD7B as a pivotal target through gene sequencing of mice engaged in voluntary running wheel exercises, positioning it as a strategy against breast cancer." (PMID 39161765, 2024). "Our study on the impact of exercise on breast cancer and the role of THSD7B gene expression, while insightful, has limitations." (PMID 39161765, 2024). "Additionally, exercise appears to inhibit breast cancer progression potentially by up-regulating THSD7B." (PMID 39161765, 2024). "The ability of exercise to inhibit cancer as well has been widely reported, our initial dataset was analyzed from a breast cancer model in mice voluntarily exercising and therefore the significantly high expression of THSD7B was selected for pan-cancer analysis." (PMID 39161765, 2024).
gastric adenocarcinoma (1 paper, 2026). "THSD7B expression was significantly elevated in gastric adenocarcinoma tissues compared with normal controls and was associated with patient survival." (PMID 42284337, 2026). "THSD7B (thrombospondin type-1 domain-containing 7B) has been implicated in several malignancies; however, its role in gastric adenocarcinoma remains unclear." (PMID 42284337, 2026). "In conclusion, THSD7B is associated with tumor progression and clinical outcomes in gastric adenocarcinoma and may be involved in the regulation of cell motility-related processes." (PMID 42284337, 2026). "This study aimed to investigate the expression pattern, clinical significance, and biological function of THSD7B in gastric adenocarcinoma." (PMID 42284337, 2026).
lung carcinoma (1 paper, 2024). "Only one article reported that mutation of THSD7B in patients inhibits cell death-related pathways, up-regulates cell invasion and metastasis pathways, and down-regulates immune response pathways, which ultimately leads to a poor prognosis in lung cancer." (PMID 39161765, 2024).
non-small cell lung carcinoma (1 paper, 2021). A group of at least three distinct histological types of lung cancer, including non-small cell squamous cell carcinoma, adenocarcinoma, and large cell carcinoma. "The only published article with THSD7B and any cancer is a GWAS study that identified a common variant (rs13405020, P < 7 × 10−6) outside of the SGS region in THSD7B in Korean patients with non-small cell lung cancer." (PMID 34368645, 2021).
tumor (6 papers, 2015 to 2026). "For instance, in DLBC and LIHC, endothelial cells show a strong positive correlation with THSD7B expression, suggesting their significant role in supporting or enhancing tumor growth and invasion, closely linked with the expression of this gene." (PMID 39161765, 2024). "The sole association with tumor size observed separately in AA (P = 0.035) and EA (P = 0.046), and in meta-analysis (P = 0.004) was with the intronic variant rs4954368 in THSD7B (thrombospondin, type I, domain containing 7B gene)." (PMID 26236334, 2015). "Of potential relevance to the pathogenesis of UL, we reported an association of the thrombospondin-encoding THSD7B with tumor size in both European and African American populations." (PMID 26236334, 2015). "We also reported moderate associations of intronic variant rs4954368 in THSD7B (thrombospondin, type I, domain containing 7B) with tumor size in race-stratified analyses and combined analyses of AA and EA in NIEHS-UFS but not in meta-analysis of risk in NIEHS-UFS and prior GWAS samples." (PMID 26236334, 2015). "In general, the use of specific therapeutic modalities to enhance THSD7B expression (e.g., material carrier-targeted delivery of THSD7B agonists, etc.)holds great promise for tumor-targeted therapy and has clinical translational value." (PMID 39161765, 2024). "And in our study stem also found that THSD7B overexpression can inhibit tumor value-added invasion, and vice versa inhibition of its expression leads to stronger tumor cell value-added invasion." (PMID 39161765, 2024). "From the heatmap, it is evident that THSD7B’s correlations with various immune cells vary, illustrating the heterogeneity of tumor microenvironments." (PMID 39161765, 2024). "THSD7B notably suppresses G2M checkpoint and E2F target pathways, potentially hindering conditions favorable for tumor cell proliferation." (PMID 39161765, 2024). "Our comprehensive analysis of THSD7B’s function in cancer through GSEA has elucidated its complex role in modulating key cellular pathways that influence tumor behavior." (PMID 39161765, 2024). "By delving deeper into THSD7B using bioinformatics and cellular biology experiments, this study seeks to elucidate its role in tumor development and progression." (PMID 39161765, 2024). "The results presented in our study illustrate the profound effects of voluntary running on tumor growth and gene expression, particularly highlighting the modulation of the THSD7B gene." (PMID 39161765, 2024). "Heterozygous variations in THSD7B can lead to reduced cell adhesion, while concurrently increasing the invasiveness and metastatic potential of tumor cells." (PMID 39161765, 2024). "This study underscores the dual role of exercise in modulating gene expression relevant to tumor growth and highlights the potential of THSD7B as a therapeutic target in cancer." (PMID 39161765, 2024). "Conversely, in other cancers, THSD7B can inhibit tumor growth by inducing apoptosis and reducing angiogenesis." (PMID 39161765, 2024). "Finally, we can also consider THSD7B as a genetic marker to cluster tumor patients and predict their prognosis." (PMID 39161765, 2024). "Additionally, the relationship between tumor mutational burden (TMB) and THSD7B expression was investigated, revealing a positive correlation in CHOL and KICH, and a negative correlation in BRCA, LUAD, STAD, UCEC, and PRAD." (PMID 39161765, 2024). "Increased THSD7B expression might inhibit the functionality of Tregs, thereby fostering an immune-enhanced tumor microenvironment favorable for tumor survival and progression." (PMID 39161765, 2024). "Our findings indicate that THSD7B may positively affect prognosis and inhibit tumor progression across a range of cancers." (PMID 39161765, 2024).
tumor (continued). "In addition, THSD7B also significantly inhibited the expression of immunosuppressive cells, suggesting its potential tumor immune microenvironment regulation function." (PMID 39161765, 2024). "Moreover, in cancers like DLBC, the activity of CD8+ T cells significantly correlate with THSD7B expression, reflecting their importance in the tumor immune response and the potential regulatory role of this gene." (PMID 39161765, 2024). "Our findings suggest that increasing THSD7B expression could disrupt the usual immune evasion tactics by tumors, thereby making the tumor environment more hostile to cancer progression and more amenable to immunotherapeutic interventions." (PMID 39161765, 2024). "This duality emphasizes the need for a nuanced understanding of THSD7B’s function in the tumor microenvironment, where it may play different roles depending on the specific cellular context and cancer type." (PMID 39161765, 2024). "This suppression could impede the conditions that typically favor rapid tumor cell proliferation, suggesting a potential tumor suppressor role for THSD7B in these regulatory pathways." (PMID 39161765, 2024). "The present study is the first to report a replicated association of THSD7B with UL, albeit with tumor size and not with risk." (PMID 26236334, 2015). "The relevance of the encoded product of THSD7B, the sole gene that consistently associated with tumor size in EA and AA populations, to UL pathogenesis is not known." (PMID 26236334, 2015). "THSD7B encodes a member of the thrombospondins (TSP) which are potent inhibitors of angiogenesis and therefore may be important in controlling tumor growth." (PMID 26236334, 2015). "Notably, upregulation of THSD7B’s in most tumors seems to imply a better prognosis, suggesting that there may be a potential regulatory role of THSD7B on tumor progression and microenvironment." (PMID 39161765, 2024). "Furthermore, the direct upstream transcription factors by which exercise regulates THSD7B expression in tumor cells remain unknown." (PMID 39161765, 2024). "Alternatively, the negative association of THSD7B with risk and positive association with tumor size in NIEHS-UFS may reflect a pathogenic mechanism whereby the tagged causal variant in THSD7B is a secondary mutation rather than a driver mutation." (PMID 26236334, 2015). "Both unmatched and matched tumor samples showed a negative correlation between THSD7B expression and methylation, particularly in COAD and LIHC." (PMID 39161765, 2024). "This contrasts with the typically suppressive behavior of Tregs, where THSD7B exhibits a negative correlation, potentially reducing their immunosuppressive effects in the tumor milieu." (PMID 39161765, 2024). "The reported association of THSD7B with tumor size may not be a spurious finding because (i) it was observed in a case-only design, (ii) the strength and direction of the association are similar in each study population, and (iii) the EA and AA groups share the allele “C” associated with tumor size." (PMID 26236334, 2015). "Additionally, THSD7B significantly enhances pathways such as angiogenesis and epithelial-mesenchymal transition (EMT), all of which are documented to potentially regulate tumor growth and metastasis." (PMID 39161765, 2024).
cancer (5 papers, 2018 to 2025). A tumor composed of atypical neoplastic, often pleomorphic cells that invade other tissues. "The prognostic implications of THSD7B expression were evident, with its expression correlating with both risk and protective factors across different cancer types." (PMID 39161765, 2024). "THSD7B is associated with cell adhesion, and THSD7B is involved in angiogenesis and oncogenic activities, hence mutations in these genes are frequently observed during cancer progression." (PMID 39161765, 2024). "The prevalence of mutations in these genes, alongside alterations in THSD7B, provides valuable insights into the molecular landscape of these cancers and could inform the development of targeted treatment strategies that address these specific genetic alterations." (PMID 39161765, 2024). "In-depth evaluation using RNA-seq data from TCGA and GTEx databases revealed significant expression differences in THSD7B across 33 types of cancer." (PMID 39161765, 2024). "Promoter methylation, a critical epigenetic regulatory mechanism affecting gene expression without altering the DNA sequence, was analyzed to explore its relationship with THSD7B expression across multiple cancer types." (PMID 39161765, 2024). "The dual role of THSD7B, both inhibiting and promoting cancer progression through different pathways, underscores the gene’s potential as a multifaceted target for therapeutic intervention." (PMID 39161765, 2024). "Our further evaluation of THSD7B’s function in pan-cancer contexts revealed significant findings via the GSEA methodology." (PMID 39161765, 2024). "Our pan-cancer analysis revealed variable expression of THSD7B across different cancer types, suggesting a complex role in oncogenesis." (PMID 39161765, 2024). "Future research should further explore the specific mechanisms by which exercise and THSD7B influence cancer progression and develop immunotherapy-enhanced strategies to change patient outcomes in clinical settings." (PMID 39161765, 2024). "Bar graphs showed changes in THSD7B copy numbers across various cancers, with significant variations in KICH." (PMID 39161765, 2024). "Post-exercise mRNA sequencing indicated a notable upregulation of THSD7B in the exercised mice, with significant alterations observed in pathways such as MicroRNAs in cancers and the Calcium signaling pathway." (PMID 39161765, 2024). "This broad impact of THSD7B underscores its potential as a therapeutic target, with implications for both direct cancer therapy and adjunctive immunotherapy." (PMID 39161765, 2024). "In cancer, THSD7B overexpression suppresses cell proliferation, viability, migration, and invasion." (PMID 41008963, 2025). "Specifically, in certain cancers, high THSD7B expression may enhance cell proliferation and metastasis, possibly through the activation of specific MicroRNAs." (PMID 39161765, 2024). "This trend implies that in certain cancer contexts, THSD7B expression may inversely affect the immunosurveillance capabilities of NK cells, potentially contributing to mechanisms of immune escape." (PMID 39161765, 2024). "In a detailed examination of THSD7B’s interaction with the immune microenvironment, our analysis reveals a nuanced and primarily beneficial role for THSD7B in modulating immune responses across various cancers." (PMID 39161765, 2024). "The insights gained into the role of THSD7B across various cancers further enhance our understanding of its potential as a therapeutic target, paving the way for more effective and personalized cancer treatments." (PMID 39161765, 2024). "Our findings illuminate the mechanisms by which THSD7B influences cancer biology and highlight the potential of exercise-induced molecular responses as a proactive measure in the prevention and treatment of cancer." (PMID 39161765, 2024). "In addition, reports on THSD7B in the field of oncology are limited, with few explorations of its specific anti-cancer mechanisms." (PMID 39161765, 2024).
cancer (continued). "Further analysis using the TCGA database’s pan-cancer dataset revealed a broadly positive correlation between THSD7B and various immune cells across different cancer types, which suggested THSD7B can be a positive factor for immune microenvironment and immunotherapy." (PMID 39161765, 2024). "In a broader cancer context, THSD7B showed considerable expression variability, being significantly downregulated in several cancers, correlating with positive prognostic outcomes in PRAD, LAML, KIRC, and GBM and highlighting its potential role as a prognostic marker and therapeutic target." (PMID 39161765, 2024). "However, THSD7B’s upregulation in aggressive cancers such as ovarian and pancreatic suggests a possible role in promoting malignancy, which could be mitigated by targeted therapies." (PMID 39161765, 2024). "To explore the therapeutic potential of exercise-induced THSD7B expression, we propose the following research directions: Mechanistic studies: To further elucidate the molecular mechanisms by which THSD7B interacts with other pathways and genes in different cancer types." (PMID 39161765, 2024). "The focus on a single gene, THSD7B, might not capture the complexity of cancer’s multifactorial nature." (PMID 39161765, 2024). "Additionally, in most certain cancer types, THSD7B shows a negative correlation with regulatory T cells (Tregs), which play a critical role in modulating the immune system, particularly in maintaining immune tolerance and suppressing excessive immune responses." (PMID 39161765, 2024).
THSD7B also shares sentences with these, for which no sentence is quoted: Airway obstruction (1 paper); atherosclerosis (1); brain tumors (1); colorectal adenocarcinoma (1); colorectal cancer (1); emphysema (1); hepatocellular carcinoma (1); liver cancer (1); lung squamous cell carcinoma (1); microcephaly (1); skin melanoma (1); Stomach cancer (1); thyroid cancer (1).